APOE (apolipoprotein E)
Diseases named in the same sentence as APOE in open-access papers (continued):
Sharing a sentence is not in itself a finding about the gene and the disease.
atherosclerosis (continued). "In this study, we used apolipoprotein E (ApoE) knockout mouse model and angiotensin II- (Ang II-) stimulated vascular smooth muscle cells (VSMCs) to elucidate the pharmacological mechanism of ISL to inhibit atherosclerosis." (PMID 32328171, 2020). "Moreover, to effectively target the particular atherosclerosis-related DC subset in vivo and the pathway involved, a DEC205-DC targeted DNA vaccine against th eCX3CR1 chemokine pathway was administrated in ApoE−/− mice." (PMID 32849502, 2020). "Altogether, these results demonstrate that constant bright light does not affect atherosclerosis in APOE*3-Leiden.CETP mice." (PMID 32915671, 2020). "In our study, we found the expression of LOC285194 was substantially lower in atherosclerotic plaques of ApoE-/- mice, suggesting that LOC285194 may play a role in atherosclerosis." (PMID 31884873, 2020). "Unfortunately, the co-ordinate reduction of both does not allow for the assessment of the contribution of the macrophage derived apoE to the attenuation of atherosclerosis independent of effects on plasma lipids." (PMID 31231209, 2019). "Levels of inflammatory cytokines have been found to be altered in gld.apoE−/− mice (mice with lupus-like features and atherosclerosis, which have absent functional Fas ligand and apolipoprotein E) treated with statins." (PMID 30959892, 2019). "In contrast to apoE−/− mice on a chow diet, administration of trehalose to female apoE−/− mice fed with a high-fat diet did not influence either the progression of atherosclerosis or the content of macrophages in the atherosclerotic plaques." (PMID 30925684, 2019). "Interestingly, while inefficient in terms of inhibition of atherosclerosis, oral trehalose was able to attenuate hepatic steatosis even in an aggressive model of the disease (HFD-fed apoE−/− mice)." (PMID 30925684, 2019). "The mice that were lack of the ApoE activity spontaneously led to atherosclerosis due to high total cholesterol levels." (PMID 30669336, 2019). "The present study shows that skeletal muscle-specific PGC-1α overexpression suppressed the progression of atherosclerosis in ApoE-KO mice without changing spontaneous activity and plasma lipid profiles." (PMID 30858489, 2019). "Atherosclerosis is not as common in rodents as in man, e.g. wildtype mice do not develop atherosclerosis; even in the often used atherosclerosis-prone ApoE−/− (knockdown) mouse model, plaques formed do not rupture." (PMID 31439044, 2019). "Studies in transgenic mice have shown that selective apoE expression only in macrophages inhibits atherosclerosis without affecting plasma lipid levels." (PMID 30909560, 2019). "In this study, we show that atherosclerosis was suppressed in the ApoE-KO/PGC-1α mice, and the mRNA expression levels of FNDC5 and the genes involved in BAIBA biosynthesis in skeletal muscle were increased about 2-fold in the ApoE-KO/PGC-1α mice." (PMID 30858489, 2019). "Double knock-out mice lacking both apoE and the RvE1 receptor ChemR23 exhibit increased atherosclerosis compared with ChemR23 expressing apoE knock-out mice after 8 and 12 weeks of high-fat diet." (PMID 31696250, 2019). "With respect to the serum lipid indexes, the ApoE-/- mice in the HFD group developed remarkable features of hyperlipidemia, with a significant increase in the TG concentration (p < 0.05), TC concentration (p < 0.001), and atherosclerosis index (p < 0.001)." (PMID 31269076, 2019). "Despite this, AAA does not normally develop in ApoE−/− but requires an additional challenge (Ang II), beyond that which triggers atherosclerosis." (PMID 30944221, 2019).
atherosclerosis (continued). "Our findings demonstrate that the presence of antibodies against the basement membrane component collagen type IV does not affect atherosclerosis development in ApoE−/− mice." (PMID 30979943, 2019). "A neutral or protective action is supported by unaltered atherosclerosis in ApoE−/− mice lacking antigen peptide transporter 1-(TAP1)-dependent MHC-I antigen presentation, despite the low number of CD8+ T cells in these animals." (PMID 31653058, 2019). "The present study demonstrated that the treatment with the anti-PCSK9 antibody mAb1 reduced atherosclerosis development, macrophage infiltration and cardiovascular inflammation and increased the number of EPC and CAC in APOE*3Leiden.CETP mice fed a Western type diet." (PMID 31366894, 2019). "In one such study, apoE−/− mice fed mixed CLA for 12 weeks showed no improvement in either en face or aortic sinus atherosclerosis." (PMID 30754681, 2019). "Notably, these NaVO3-induced atherosclerotic pathologies in ApoE−/− mice were prevented by NAC treatment, indicating that ROS is required for NaVO3-driven atherosclerosis." (PMID 31817202, 2019). "Removal of endothelial cilia in Apoe−/− mice lacking apolipoprotein E increased atherosclerosis when they were fed with a high-fat, high-cholesterol diet, due to the reduced activity of endothelial nitric oxide synthase (eNOS)." (PMID 30884815, 2019). "It has been suggested that apoE may be involved in endogenous antigen presentation to activate NKT cells, so this model may confound analysis of NKT cell involvement in atherosclerosis." (PMID 31540125, 2019). "In contrast, systemic ACAT1 deficiency ApoE−/− and LDL−/− mice does not affect atherosclerosis, but these mice develop dermal xanthomas and form cholesterol deposits in the brain." (PMID 31653058, 2019). "Such a phenomenon can be considered as one of the factors accelerating atherosclerosis development, since it has been shown in both non-CKD and CKD patients that APOE level in APOB-containing lipoproteins positively associates with incident CVD risk." (PMID 30851738, 2019). "Deficiency of eNOS increases atherosclerosis and AAA in apoE (−/−) mice without altering arterial blood pressure, body weight, serum cholesterol concentrations, or distribution of lipoprotein cholesterol." (PMID 29849906, 2018). "We found that a significant increase in the dose of Ang II to 3 mg/kg/day in BMT ApoE−/− mice was required to increase aneurysm formation and atherosclerosis to the level observed in non-BMT ApoE−/− mice treated with 0.8 mg/kg/day Ang II." (PMID 30048944, 2018). "To further study whether FGF21 inhibits atherosclerosis via ameliorating Fas-mediated apoptosis in apoE−/− mice, we measured the mRNA and protein expression of Fas and FADD in the apoE−/− mice and apoE−/− mice treated with FGF21." (PMID 30157856, 2018). "High-fat diet (HFD)-fed apolipoprotein E (apoE)−/− mice and oxidized low-density lipoprotein (ox-LDL)-stimulated human aortic endothelial cells (HAECs) were established as in vivo and in vitro models of atherosclerosis." (PMID 29387339, 2018).
atherosclerosis (continued). "Exposure of peritoneal macrophages to an inflammatory lipid reduces Klf4 and increases M1 mRNAs, the latter induced to a greater extent in Klf4(f/f);Lys-Cre macrophage, and absence of myeloid Klf4 augments atherosclerosis in ApoE-/- mice." (PMID 29324844, 2018). "ApoE was initially recognized for its importance in lipoprotein metabolism and cardiovascular disease because dysfunction of ApoE protein results in familial dysbetalipoproteinemia (type III hyperlipoproteinemia), which often leads to atherosclerosis." (PMID 30305304, 2018). "The different results between these recent studies and our study are likely due to the atherosclerosis model, the HFD duration in ApoE(−/−) mice as all plaques that we analyzed at 6 or 12 weeks (n = 7) were monoclonal and/or a difference between the Confetti and Rb reporters." (PMID 29802249, 2018). "It has, however, been reported that STZ-mediated induction of aortic sinus atherosclerotic plaque development in apoE-KO mice appears to be time dependent, with STZ-treatment exhibiting more pronounced effects early in atherosclerosis development and diminished effects with increased time." (PMID 30356742, 2018). "Similarly, apoE knockout (Apoe−/−) mice are hypercholesterolemic due to impaired hepatic clearance of TRL remnants, which leads to the development of atherosclerosis even when the mice are fed a low fat diet." (PMID 30282955, 2018). "This was recently determined by the generation of hyperlipidemic ApoE−/− mice lacking ERV1/ChemR23, which exhibit exacerbated atherosclerosis with larger lesions containing more macrophages compared with ERV1/ChemR23 expressing ApoE−/− littermates." (PMID 30487747, 2018). "Deletion of PXR attenuates the development of atherosclerosis in PXR and apoE double knockout (PXR-/- and ApoE-/-) mice, which may be associated with the reduction of CD36 expression and lipid uptake in macrophages." (PMID 30319417, 2018). "Together, such findings highlight the complexity through which apoE contributes to regulate microRNA signaling to suppress inflammation and atherosclerosis in the absence of plasma lipid reduction." (PMID 29789495, 2018). "Although RAGE deficiency attenuates atherosclerosis in ApoE null mice, effects on vascular calcification have not been reported in RAGE/ApoE null mice." (PMID 30467547, 2018). "Furthermore, IKBKE ablation in apoE−/− mice enhances NLRP3 inflammasome priming and promotes atherosclerosis." (PMID 30134788, 2018). "Apolipoprotein E is an important glycoprotein that acts as a ligand for chylomicron-remnant receptor, and lack of apolipoprotein E is known to induce atherosclerosis in mice." (PMID 29867020, 2018). "In the case of ApoE(−/−) ATM(+/−) mice, atherosclerosis was accelerated by a high-calorie diet." (PMID 30513990, 2018).
atherosclerosis (continued). "Atherosclerosis was increased in the descending aorta and aortic root in OGG1−/− ApoE−/− mice compared with controls but markedly decreased in both vascular beds in SM22α-OGG1 ApoE−/− mice; this protective effect was lost in SM22α-OGG1K-R ApoE−/− mice." (PMID 29643057, 2018). "Transient arterial ligation in ApoE knockout mice resulted in atherosclerosis in the transiently ligated vascular segment but not on the not-ligated contralateral side." (PMID 30289932, 2018). "In this study, we investigated the role of FGF21 in suppressing the progression of atherosclerosis, and we tested the hypothesis that FGF21 could inhibit Fas-mediated apoptosis in apoE−/− mice." (PMID 30157856, 2018). "For instance, the HDL particles derived from the SR-BI−/− × Apoe−/− mice, which lacked apoE, failed to protect the endothelium from atherosclerosis." (PMID 30282955, 2018). "In the present study, we extend these findings by establishing that long term dietary supplementation with SM does not increase atherosclerosis in high fat-fed, and decreases atherosclerotic lesion development in the aortic arch of chow-fed apoE-/- mice." (PMID 29240800, 2017). "SM consumption did not increase circulating SM levels or atherosclerosis in high fat-fed apoE-/- mice." (PMID 29240800, 2017). "Consistently, en face staining of lipid-rich lesions from mouse aortas showed that the total lesion area was significantly lower in aortas from ApoE/mitoNEET-Tg than those from ApoE knockout mice, indicating that overexpression of mitoNEET in PVAT inhibits atherosclerosis in mild cold conditions." (PMID 29311966, 2017). "However, the expression of inflammation-related genes, involved in atherosclerosis development, were markedly elevated in the aortas of NA/STZ-ApoE KO mice, as compared with untreated ApoE KO mice." (PMID 28777298, 2017). "A more heterogeneous PWV-distribution in the ApoE (−/−)-animals could be observed compared to the C57BL/6J-mice, representing the local character of lesion development in atherosclerosis." (PMID 29037199, 2017). "This study establishes that dietary SM does not affect circulating SM levels or increase atherosclerosis in high fat-fed apoE-/- mice, but it is anti-atherogenic in chow-fed apoE-/- mice." (PMID 29240800, 2017). "Whilst high doses of exendin-4 (24 nmol kg−1day−1) for 4 weeks suppressed atherosclerosis in ApoE−/− mice fed a standard diet monthly doses of 0.4 mg taspoglutide for 12 weeks did not reduce plaque area in hyperglycemic ApoE−/− mice fed a 45% fat diet." (PMID 29110715, 2017). "A large cohort of pro-atherogenic ApoE-null mice were placed on a western diet, treated with vehicle, trehalose or sucrose (a similar non-reducing disaccharide), and atherosclerosis was quantified at the level of the aortic root (details are this study)." (PMID 28589926, 2017). "ApoE (-/-) mice fed with high-fat diets (HFD) display high lipid levels, excessive cholesterol in the blood vessels and atherosclerotic symptoms, making this an acknowledged model for investigating atherosclerosis." (PMID 28536634, 2017). "Expression of key chemokines previously linked to atherosclerosis, including CCL2 and CXCL10 as well as CCL5, was significantly attenuated by AVE0991 treatment, in the PVAT of ApoE−/− mice, while no change was seen in the aortic wall itself." (PMID 27935022, 2017). "The further reduction in CF induced by Up4A, as well as upregulation of the net vasoconstrictor P2X1R in ApoE KO + HFD mice, may be due to advanced atherosclerosis." (PMID 28929376, 2017).
atherosclerosis (continued). "Compared with the model group, the media layer of apoE-/- mice showed inhibited VSMC proliferation and increased autophagy with Paeonol treatment; therefore, Paeonol induced VSMC autophagy and protected against cell proliferation in atherosclerosis." (PMID 29354055, 2017). "The authors further reported that the biallelic deletion of Cd39 on the ApoE KO background [double KO (DKO)] did not appear to exacerbate atherosclerosis, albeit the phenotype was heterogeneous." (PMID 28487312, 2017). "Sudan IV staining for atherosclerosis lesions in 8 and 20 weeks old mice confirmed atherosclerosis development in the ApoE−/− mice fed 12 weeks of WD but not in 8 week old Chow fed ApoE−/− mice." (PMID 28970806, 2017). "Moreover, signals from targeted microbubbles increased from 8wks to 32wks age (P<0.05 for trend) in ApoE-/- mice, indicating the upregulation of VCAM-1 with the progression of atherosclerosis." (PMID 28982198, 2017). "In a different study, treatment of ApoE-/- mice with an AT1 receptor antagonist and simultaneous infusion with angiotensin II inhibited progression of atherosclerosis by decreasing the expression of pro-inflammatory markers and ROS production from the endothelium." (PMID 28688452, 2017). "Given the reported link between psoriasis and coronary artery disease, the biological relevance of the autoantigen to atherosclerosis was tested in vitro using a truncated (t) form of the mouse homolog of hCAP18, CRAMP, on splenocytes from athero-prone ApoE(-/-) mice." (PMID 29091929, 2017). "Since 1998, when the ApoE KO mouse model was employed for studies of atherosclerosis and hyperlipidemia, it has not been shown how LDLs contribute to specific effects on AdvSCA-1+ cells." (PMID 28757161, 2017). "Since the IKKαf/f:MLysCre/apoE-/- mouse is incapable to activate either canonical or non-canonical pathway, it can be used to test macrophage-specific let-7g effects on atherosclerosis." (PMID 29254143, 2017). "Taken together, these results demonstrated that OSMR ablation in ApoE−/− mice attenuated HFD-induced atherosclerosis and that this effect was not dependent on dyslipidemia." (PMID 28258089, 2017). "To study whether the lack of CysC in mice had any effect on autophagy and cell death in atherosclerosis, we analysed Atg5 and LC3β for autophagy and TUNEL for apoptosis in lesions in apoE−/−CysC−/− compared with apoE−/−CysC+/+ mice." (PMID 27079462, 2016). "Our results add considerably to these earlier data by showing that although experimental induction of psoriasis-like skin lesions led to systemic inflammation, atherosclerosis in the ApoE−/− model was not significantly affected." (PMID 27401543, 2016). "As inflammation is a major contributing factor in atherosclerosis progression and plaque instability, we next analysed if absence of ADAMTS4 influences the plasma inflammatory cytokines between 18 weeks old sex matched ApoE−/− and ApoE−/−Adamts4−/− mice." (PMID 27491335, 2016). "Compared with 12-weeks old ApoE−/− mice, reduced atherosclerosis was observed in ApoE−/−Adamts4−/− male mice but not female mice." (PMID 27491335, 2016). "Cyp27a1(−/−)/Apolipoprotein E(−/−) double knockout mice (DKO) fed a western diet failed to develop atherosclerosis." (PMID 28149711, 2016). "Using a double POLG/ApoE low-density lipoprotein (LDL) receptor knock-out, it was shown that instability of mtDNA might contribute to atherosclerosis." (PMID 27213333, 2016). "Here, we utilize a distinct approach to investigate the contribution of a hyperlipidemic environment on the development of arthritis and atherosclerosis in mice lacking ApoE." (PMID 27287704, 2016).